GRPEL1 (GrpE like 1, mitochondrial)
Description:
Essential component of the PAM complex, a complex required for the translocation of transit peptide-containing proteins from the inner membrane into the mitochondrial matrix in an ATP-dependent manner (By similarity). Seems to control the nucleotide-dependent binding of mitochondrial HSP70 to substrate proteins.
Synonyms: FLJ25609; GrpE; hMGE; mt-GrpE#1
Tractability: PROTAC: ubiquitination databases record sites on it; its protein half-life has been measured.
Gene: Protein-coding gene on chromosome 4 (7,058,643 to 7,068,145, reverse strand). Ensembl gene ENSG00000109519.
Subcellular location: Mitochondrion matrix
Subcellular location (Human Protein Atlas): Mitochondria; Nucleoplasm
Pathways (Reactome):
Disease: Dengue Virus-Host Interactions
Protein localization: Mitochondrial protein import
Gene Ontology:
Molecular function: adenyl-nucleotide exchange factor activity; identical protein binding; protein binding; protein homodimerization activity; protein-folding chaperone binding
Biological process: intracellular protein transport; protein import into mitochondrial matrix; protein folding
Cellular component: mitochondrial matrix; mitochondrion; mitochondrial inner membrane; PAM complex, Tim23 associated import motor; TIM23 mitochondrial import inner membrane translocase complex
Genetic constraint (gnomAD): Loss-of-function variants: 9 observed, 16.18 expected, observed/expected ratio (o/e) 0.56, 90% interval 0.33 to 0.97. The upper end of that interval is the gene's LOEUF score, 0.97, which puts it in group 4 of 6, group 1 being the genes least tolerant of losing a copy. Missense variants: 254 observed, 245.57 expected, observed/expected ratio (o/e) 1.03, 90% interval 0.93 to 1.15. Synonymous variants: 98 observed, 99.49 expected, observed/expected ratio (o/e) 0.99, 90% interval 0.83 to 1.16.
Homologues: Orthologues: chimpanzee GRPEL1 (100% identical), macaque GRPEL1 (99% identical), dog GRPEL1 (91% identical), mouse Grpel1 (88% identical), guinea pig GRPEL1 (88% identical), rat Grpel1 (82% identical), zebrafish grpel1 (71% identical), tropical clawed frog grpel1 (69% identical), Drosophila melanogaster Roe1 (45% identical), Caenorhabditis elegans C34C12.8 (38% identical). Paralogues in human: GRPEL2 (42% identical).
Diseases named in the same sentence as GRPEL1 in open-access papers:
GRPEL1 is named in the same sentence as 12 diseases in open-access papers, as found by Europe PMC text mining. Sharing a sentence is not in itself a finding about the gene and the disease. The quoted sentences say what the papers report.
breast carcinoma (1 paper, 2019). "Through comparison of mRNA levels between adjacent normal tissues and breast cancer tissues, we found that CSNK2B (p = 5.78e-33) and GRPEL1 (p = 4.19e-07) were significantly upregulated in tumor tissues." (PMID 31781497, 2019). "High expression of CSNK2B (p = 0.0041, HR = 1.37), GRPEL1 (p = 0.0200, HR = 1.29) and QARS (p = 0.0350, HR = 1.26) were corelated with worse prognosis in breast cancer patients, whereas CCND3, HDAC3, SH3BGRL3, SRM, and UBE2D4 were not correlated with OS." (PMID 31781497, 2019).
hemorrhagic stroke (1 paper, 2024). A stroke caused by a bleed on the brain. "A study focusing UPRmt in hemorrhagic stroke showed a mechanism between GrpE like 1, mitochondrial (GrpEL1), a nucleotide exchange factor, and mitochondrial HSP70 (mtHSP70)." (PMID 38321473, 2024). "Although mtHSP70 upregulation was observed in oxyhemoglobin-induced cell model of hemorrhagic stroke, the constitutive binding of GrpEL1 and mtHSP70 was decreased, which resulted in the UPRmt inhibition that contributed to mitochondrial dysfunction and impairment." (PMID 38321473, 2024).
kidney stone (1 paper, 2025). "Five of these protein ratio pairs positively promote kidney stone development: BAIAP2/MME protein level ratio, GRPEL1/MME protein level ratio, HLAE/IL15 protein level ratio, CEACAM1/GGT1 protein level ratio and BTN2A1/IL18BP protein level ratio." (PMID 40673688, 2025).
infection (11 papers, 2014 to 2025). The state of being infected such as from the introduction of a foreign agent such as serum, vaccine, antigenic substance or organism. "Representative genes from this group (GrPEL1, GrENG1 and GrEXPB2) showed relatively high expression in pre-J2s and during early stages of infection." (PMID 25606855, 2015).
tumor (2 papers, 2019 to 2026). "Targeting the c-Myc/GRPEL1 axis to block FASN-regulated FA synthesis inhibited PDAC cell proliferation and tumor growth in both cell models and patient-derived organoids (PDOs), whereas FA supplementation partially reversed this inhibitory effect." (PMID 41644513, 2026).
neurodegenerative disease (1 paper, 2025). A disorder of the central nervous system characterized by gradual and progressive loss of neural tissue and neurologic function. "GRPEL1 also contributes significantly to the mechanisms of neurodegenerative diseases." (PMID 41204552, 2025).
GRPEL1 also shares sentences with these, for which no sentence is quoted: cancer (2 papers); tuberculosis (2); COVID-19 (1); glioma (1); subarachnoid hemorrhage (1); Wolfram syndrome (1).